CXCL12 (C-X-C motif chemokine ligand 12)
Diseases named in the same sentence as CXCL12 in open-access papers (continued):
Sharing a sentence is not in itself a finding about the gene and the disease.
atherosclerosis (continued). "Strikingly, 10 genes exhibited shared dysregulation in both aging and atherosclerosis, including Vcam1, Apoe, Gdf15, Timp1, Cxcl12, Hspd1, Serpine1, App, Eln, and Hif1a, suggesting their potentially critical roles in the atherosclerosis driven by aging in HGPS mice." (PMID 41209003, 2025). "CXCL12 is thought to promote atherosclerosis progression by signaling downstream of CXCR4." (PMID 39483879, 2024). "Still, some chemokines may be useful as biomarkers since augmented levels of CCL5 or CXCL12 correlate with the severity of atherosclerosis or CAD respectively." (PMID 35600479, 2022). "CXCL12 is involved in the release of inflammatory factors during the immune process and may influence the pathogenesis of atherosclerosis and osteoarthritis." (PMID 35702353, 2022). "The measurement of CXCL12 expression by the simple flow cytometry method could represent a potential useful biomarker in the very first phases of atherosclerosis." (PMID 34987703, 2021). "However, this review focuses specifically on the role of CXCR4 and CXCR7 (ACKR3) receptors, their complex mutual relationship and their interaction with the ligand CXCL12 (SDF-1) in atherosclerosis." (PMID 34494495, 2021). "However, in contrast to EC CXCL12 knockout, EC CXCR4 knockout caused endothelial leakage and leukocyte invasion, implying that EC CXCR4 protects against atherosclerosis by preserving endothelial integrity and barrier function." (PMID 34494495, 2021). "Mice treated with the CXCR4 inhibitor AMD3465 had increased lesions and leucocytosis in the plaque, suggesting that CXCL12 might resist atherosclerosis by regulating neutrophil release." (PMID 35668739, 2021). "In addition, human endothelial cell-derived ApoMVs carrying miR-126 upregulate CXCL12 in vascular cells, which recruits the incorporation of Sca-1+ progenitor cells to promote vascular protection and inhibit atherosclerosis." (PMID 33134295, 2020). "The increased extracellular HSP27 released from platelets synergistically activated by a combination of collagen and CXCL12 might also be involved in the progression of atherosclerosis." (PMID 33119719, 2020). "These GWASes demonstrate that CXCL12 may emerge as a potential therapeutic target for atherosclerosis and thrombosis." (PMID 30844764, 2019). "Furthermore, miR-126 counteract atherosclerosis inducing CXCL12 production and influence inflammation by controling endothelial expression of VCAM1." (PMID 29937989, 2018). "Previous studies have shown the function of CXCL12 in the process of atherosclerosis." (PMID 28903360, 2017). "Besides the already described chemokines involved in atherosclerosis, in the recent years, more and more research has been focusing on two yet undiscussed chemokines, being CXCL12 and MIF." (PMID 26257740, 2015). "Aged ApoE−/− mice with advanced atherosclerosis have lower levels of CXCL12 in serum and bone marrow than their age matched controls, indicating that CXCR4-CXCL12 axis may counter plaque development." (PMID 24741577, 2014). "Further research is definitively needed to improve phenotypical and functional characterization of vascular progenitor cell subsets in context of atherosclerosis before a role of the CXCR4/CXCL12 axis in their mobilization and potential functions in this pathology can be investigated in detail." (PMID 24966838, 2014). "The protective role of CXCL12 in diet-induced atherosclerosis has been discovered recently." (PMID 23613728, 2013). "CXCR4, the specific receptor for CXCL12, is expressed in the vascular cells and macrophages and plays a crucial role in leukocyte recruitment into vessel walls and monocyte–macrophage differentiation, as well as macrophage polarization, during the development of atherosclerosis." (PMID 36670934, 2022). "Thus, CXCL12 and its receptors are speculated to be potential therapeutic targets and biomarkers in atherosclerosis and other CVDs." (PMID 34494495, 2021).
atherosclerosis (continued). "Likewise, CXCL12 facilitates the removal of apoptotic platelets by monocytes and macrophages, but enhances the conversion of macrophages to foam cells, thus promoting atherosclerosis." (PMID 34494495, 2021). "Besides these effects on progenitor cells, mediating beneficial effects on atherosclerosis, CXCL12/CXCR4 may also influence disease development by influencing various atherosclerosis-related cells." (PMID 26257740, 2015). "For instance, current evidence suggests that the therapeutic application of miR-181b may limit the release of CXCL1 from the vascular endothelium and thereby reducing atherosclerosis, whereas the endothelial delivery of miR-126-3p boosts atheropotective CXCL12 expression." (PMID 26001902, 2015). "However, short term heparin application may alter the prognosis during acute ischemia, which is an important driver of atherosclerosis by enhancing the pool and number of circulating monocytes and progenitor cells via CXCL12." (PMID 25152735, 2014). "For example, the binding of CXCR4 to CXCL12 promotes macrophage autophagy through the PI3K/AKT/mTOR pathway, which alleviates atherosclerosis and improves myocardial structure." (PMID 40535169, 2025). "In macrophages, CXCL12 has been proven to inhibit ABCA1‐dependent cholesterol efflux and aggravate atherosclerosis." (PMID 39763069, 2025). "Our RNA‐seq results and further experiments revealed that early growth response 1 (EGR1)/CXCL12 axis is the downstream effector of endothelial MAPK6 in DSS‐induced inflammation and atherosclerosis." (PMID 39763069, 2025). "Blockade of CXCR4 can inhibit the activation of CXCR4 after binding with CXCL12 and regulate autophagy through the PI3K/AKT/mTOR pathway to improve and reduce atherosclerosis and improve cardiac structure." (PMID 40535169, 2025). "In particular, ACKR3’s role in regulating CXCL12 bioavailability and modulating CXCR4-mediated chemotaxis positions it as an intriguing target to fine-tune B-cell activity in atherosclerosis." (PMID 40986007, 2025). "These lines of evidence suggest that the role of CXCL12 and CXCR4 in atherosclerosis is still under debate." (PMID 36670934, 2022). "As vascular CXCL12 and CXCR4 were shown to significantly contribute to atherosclerosis, the aim of this study was to decipher the role of arterial ACKR3 in atherosclerosis, which is an important missing link in this chemokine-axis." (PMID 35674847, 2022). "In contrast to their findings regarding EC-specific CXCL12, EC-specific CXCR4 was shown to limit atherosclerosis by supporting endothelial barrier function." (PMID 33503867, 2021). "In view of the CXCR4 protein in atherosclerosis, the function and expression of two alternative ligands of CXCR4, MIF and CXCL12 were summarized and compared." (PMID 31004184, 2019). "In atherosclerosis, recent cell-specific knockouts of CXCR4 as well as the study of neutrophil-mediated atherogenic effects has established that the CXCR4/CXCL12 axis has cell-dependent protective or exacerbating effects." (PMID 29581527, 2018). "Lastly, miR-126a-3p has also a regulatory role for the expression of CXCL12 via the inhibition of CXCR4 by RGS16, a signaling pathway that is involved in atherosclerosis and inflammation." (PMID 26956024, 2016). "Recent years, CXCL12 and macrophage migration inhibitory factor (MIF) have gained a lot of interest in the field of atherosclerosis research." (PMID 26175090, 2015). "However, as MIF seems to have more pro-atherosclerotic effects, CXCL12 may have a protective function, although results are still contradictory at some level and future research should further elucidate the exact role of these chemokines in atherosclerosis." (PMID 26257740, 2015). "CXCL12 and its main receptor CXCR4 are expressed on various atherosclerosis-related cell types, like ECs, SMCs, and leukocytes." (PMID 26175090, 2015).
atherosclerosis (continued). "The importance of the CXCL12/CXCR4 axis in progenitor cell homing and mobilization will be addressed, as will be the function of CXCR4 in different cell types involved in atherosclerosis." (PMID 24966838, 2014). "CXCL12, also known as SDF‐1, has been proven to be the driving factor of atherosclerosis." (PMID 39763069, 2025). "While CXCL12 is considered to act primarily as a proatherogenic chemokine, activation of the CXCL12/CXCR4/CXCR7 axis can in fact lead to both the progression and stabilization of atherosclerosis." (PMID 36077592, 2022). "CXCL12 and CXCR4 coordinatively play a pivotal role in atherosclerosis and arterial injury." (PMID 34552562, 2021). "It has been known that platelets are also involved in the development and manifestation of atherosclerosis by secreting chemokines including CXCL4 or platelet factor 4, CCL5, CXCL12 to recruit monocytes or neutrophils to promote local inflammatory processes at sites of vascular injury." (PMID 34901005, 2021). "For instance, miR-126-3p delivered by EC apoptosis bodies inhibits expression of regulator of G-protein signaling 16 (RGS16) to activate C-X-C motif chemokine ligand 12 (CXCL12) and its receptor, C-X-C motif chemokine receptor 4 (CXCR4), thereby reducing atherosclerosis." (PMID 33391525, 2021). "More recently, a study suggested that CXC chemokine ligand 12 (CXCL12) activates the GSK3β/β-catenin/TCF21 signaling pathway through CXCR4, a specific receptor for CXCL12, inhibiting cholesterol efflux from macrophages and promoting atherosclerosis." (PMID 33729392, 2021). "Here, the authors have designed a peptide-based ectodomain mimic of the chemokine receptor CXCR4 that selectively targets MIF but not CXCL12 and blocks experimental atherosclerosis in vivo." (PMID 33239628, 2020). "The relevance of the cell-specific contribution of CXCL12 and its receptor CXCR4 in the progression of atherosclerosis has been extensively proven, thus further linking the miR-126 duplex to atherosclerosis development." (PMID 32733281, 2020). "In fact, the interaction of miR-126-3p or miR-126-5p with CXCL12 does not play a significant role in the context of atherosclerosis." (PMID 26001902, 2015). "In the present study, we observed that patients with CAS had significantly elevated serum levels of CX3CL1, CXCL12, CCL19, CCL21, CCL2, and CCL5 compared to control individuals, suggesting that these chemokines are intricately involved in the initiation and progression of atherosclerosis." (PMID 40236901, 2025). "CXCR4 is one of the specific receptors for CXCL12, and its activation upon binding with CXCL12 plays a role in signal transduction related to inflammation, chemotaxis, survival, and proliferation, with high expression of CXCR4 being closely related to the stability of atherosclerosis." (PMID 40535169, 2025). "Considering the relevant role of the CXCL12–CXCR4 axis in vascular homeostasis and the potential of EPCs and SMCs to release CXCL12 and express CXCR4, we analyzed the engagement of the CXCL12–CXCR4 axis in various modes of EPC–SMC interaction relevant for injury- and lipid-induced atherosclerosis." (PMID 35055054, 2022). "We determined the expression of Cxcl12, Vcam1, Scf (Kitl) and Angpt1, thus sampling the canonical factors supplied by various niche cells to promote HSPC retention and quiescence in steady state that decline after acute MI37 in mice with hypertension or atherosclerosis." (PMID 35747128, 2022). "Moreover, the CXCL12/CXCR4 interaction activates the GSK-3β/β-cateninT120/TCF21 signalling pathway to inhibit ABCA1-dependent cholesterol efflux from macrophages to Apo-A1 and aggravate atherosclerosis." (PMID 34494495, 2021). "Specific temporal and spatial modulators of CXCL12, CXCR4, and ACKR3, in addition to specific modulators of downstream signalling, should be explored to suppress their unwanted action in the pathogenesis of atherosclerosis and to enhance their desirable effects." (PMID 34494495, 2021).
atherosclerosis (continued). "Despite the extensive evidence that inflammation is a key component of atherosclerosis, there has not been a large GWAS signal in loci harboring pro-inflammatory cytokines or chemokines, IL6R and CXCL12 loci being notable exceptions." (PMID 36792607, 2023).
hepatocellular carcinoma (88 papers, 2006 to 2026). A malignant tumor that arises from hepatocytes. "EPAS1, which was found in the LIHC top 10 TFs of three methods, is linked to CXCL12, which plays an important role in metastasis formation of hepatocellular carcinoma by promoting the migration of tumor cells." (PMID 28347313, 2017). "Another recent study showed that hepatocellular carcinoma (HCC) upregulates CXCL12 to recruit Treg cells and tumor-associated macrophages (TAMs), promoting tumor progression and metastasis." (PMID 38786066, 2024). "Some studies have demonstrated that CXCL12 promotes the growth, invasion and angiogenesis of hepatocellular carcinoma, which is considered a potential biomarker for hepatocellular carcinoma." (PMID 38678587, 2024). "In hepatocellular carcinoma, the activation of the CXCL12/CXCR4 axis via the STAT3 signaling pathway promotes protein expression of CSC markers SOX2 and CD133, enhancing the spheroid-forming capacity and invasiveness of liver cancer cells." (PMID 38920657, 2024). "In conclusion, these results indicate CXCL12 expression closely related to a high aggregation of tumor infiltrating immune cells in hepatocellular carcinoma tissues and that high CXCL12 expression cases have an immune microenvironment adapted to TLS formation." (PMID 38767772, 2024). "For instance, the relationship between PGK1 and CXCR4/CXCL12/β-catenin has been established in gastric cancer and hepatocellular carcinoma." (PMID 38163864, 2024). "The chemokine, C-X-C motif chemokine ligand 12 (CXCL12) and its G-protein-coupled receptor (GPCR) and C-X-C chemokine receptor type 4 (CXCR4), are closely associated with promoting hepatocellular carcinoma (HCC) chemotaxis and metastasis." (PMID 37251542, 2023). "Our study shows that the cooperation between LX2 cells and hepatomas increases the total level of CXCL12, potentially promoting the activity and aggressiveness of cancer cell lines through the CXCL12 ligand–CXCR4 receptor interaction." (PMID 37762298, 2023). "In hepatocellular cancer, CAFs-secreted CXCL12 drives the M2 macrophage polarization and the release of plasminogen activator inhibitor‐1 (PAI-1), ultimately promoting tumor progression." (PMID 37821959, 2023). "CXCL12 concentration in the medium of untreated LX2 was twice as high compared to untreated hepatomas, indicating that fibroblasts were the major producers of this cytokine in this system." (PMID 37762298, 2023). "High baseline secretion of CXCL12 by LX2 cells remained unaltered following treatment with hepatoma-conditioned media." (PMID 37762298, 2023). "CXCL12/CXCR4 axis blockade in combination with sorafenib treatment was reported to inhibit hepatocellular cancer growth." (PMID 30813533, 2019). "The CXCR4/CXCL12 has multiple functions at various points in the progression of hepatocellular carcinomas (HCCs)." (PMID 26404566, 2015). "In hepatocellular carcinoma, CXCR4 and CXCL12 have been associated with variations in the cell cycle resulting in increased risk of metastasis formation in bone, and elevated levels of the chemokine enhances migration of the tumor cells." (PMID 26560447, 2015). "In this study, we demonstrate for the first time that IFF can induce invasion of hepatocellular carcinoma cells through the formation of autologous transcellular gradients of CXCL12." (PMID 26560447, 2015). "Previous study indicated that CXCR4 were highly expressed in HCC, and its ligand chemokine (C-X-C motif) ligand 12 (CXCL12) CXCL12 can stimulate human hepatoma cell growth, migration and invasion." (PMID 24586606, 2014). "Expression analysis and functional assays were performed in vitro to elucidate the impact of CXCL12 on human hepatoma cells lines." (PMID 16819541, 2006). "In hepatocellular carcinoma (HCC), combined spatial transcriptomics and proteomics uncovered CXCL12+ tumor-associated endothelial cells that mediate immunosuppression by recruiting MDSCs and inhibiting CD8+ T cells - a resistance mechanism missed in bulk analyses." (PMID 40693266, 2025).